IDO1 (indoleamine 2,3-dioxygenase 1)
Diseases named in the same sentence as IDO1 in open-access papers (continued):
Sharing a sentence is not in itself a finding about the gene and the disease.
tumor (continued). "In this context, non-steroidal anti-inflammatory drugs, which are COX-2 inhibitors, could at the same time lower PGE2 levels and IDO1 expression, leading to Treg cell downmodulation as seen in the reversion of tumor immune evasion in cancer models." (PMID 32051758, 2020). "Because IDO1 can inhibit the anti-tumor effect of T cells by degrading tryptophan." (PMID 33552086, 2020). "In cancer, expression of IDO1 has been observed in both tumor and immune cells." (PMID 33584686, 2020). "Based on the expression, clinical outcome results and the enzyme activity to catalyse tryptophan to kynurenine, IDO1 may act as a more important role in tumour, so we choose IDO1 as the protagonist of the follow‐up analysis." (PMID 32227579, 2020). "We also found that CTLA4 and IDO1, two well‐known immune checkpoints, were significantly higher in both tumor tissues and NATs than in healthy tissues, while the expression levels of VEGFB and LAG3 increased progressively in healthy tissues, NATs and tumor tissues." (PMID 33033616, 2020). "Notably, this upregulation of the kynurenine/tryptophan ratio was also correlated with a higher density of IDO1 expression in pre-treated tumor samples." (PMID 32194552, 2020). "As IDO1 is expressed at low levels in normal tissues but is upregulated in tumours, inhibition of IDO1 would not be expected to cause major adverse effects." (PMID 31819194, 2020). "Actually, IDO1 is expressed in two compartments, TCs and TILs, respectively, and the tumour microenvironment may be changed by their interaction, leading to variant outcomes of tumour prognosis." (PMID 32227579, 2020). "In fact, IDO1 is expressed in immune cells and in tumor cells themselves." (PMID 33584695, 2020). "Our results indicated that IDO1 participated in tumour immune process." (PMID 32227579, 2020). "Indoleamine 2,3-dioxigenase 1 (IDO1) is expressed by various cancer cells and immune cells in the tumor microenvironment, including T cells, dendritic cells (DCs), tumor-associated macrophages, mesenchymal stromal cells (MSCs), and myeloid-derived suppressor cells (MDSCs)." (PMID 33425745, 2020). "We quantified CD8+ T cells by immunofluorescent staining and image analysis and correlated the results to IDO1 expression in the corresponding tumor and in tumor endothelial cells (endothelial fraction of the TRAP immunoprecipitation), and found a positive correlation in both cases." (PMID 32231867, 2020). "On the other hand, the induction of PD-L1 and IDO1 expression may dampen the anti-tumor CTL response, suggesting that IL-27 and IFN-γ may have dual effects in tumors." (PMID 32093058, 2020). "In vivo, IDO1 is best known for its immunoregulatory role in mediating tumor immune evasion." (PMID 32973768, 2020). "In PDAC murine model, an IDO1 inhibitor was shown to improve the anti-tumor efficacy of GVAX." (PMID 33718118, 2020). "Additionally, a recent study further showed that knockdown of IDO1 by shRNAs mainly increased tumor infiltration of neutrophils and delayed tumor progression in a xenograft model of CT26 and MC38 murine CRC cells." (PMID 33419310, 2020). "In the PAM50 luminal cohort, the subset of immune signatures (PD-L1, TIGIT, IDO1, TIS) trending lower in LR may have been linked to a suppressive immune response among recurrent luminal tumours." (PMID 32825588, 2020). "In addition, other studies have shown that the canonical Wnt signaling in tumor DCs promote the metabolism of vitamin A and tryptophan through the induction of enzymes involved in retinoic acid (RA) synthesis and indoleamine 2,3-dioxygenase-1 (IDO)." (PMID 32132993, 2020). "IDO-1 activity can lead to the inhibition of T-cells by suppression of effector T-cell function and activation of regulatory T-cells, which is a potential mechanism enabling tumor cells to avoid host immune response." (PMID 32260340, 2020).
tumor (continued). "A limitation in this study is that epacadostat is likely to impact all IDO1-expressing cells within the tumor microenvironment, and a specific role of endothelial IDO1 in affecting T-cell activation can only be formally proven by specifically knocking out IDO1 in endothelial cells." (PMID 32231867, 2020). "IDO-1 expressed by cancer cells and dendritic cells is a starter enzyme for the tryptophan metabolism pathway and suppresses the immune response against the tumor." (PMID 33375686, 2020). "IDO1 and Arg1 can also be expressed in the same tumor microenvironment." (PMID 33392202, 2020). "Up-regulation of tumor IDO1 expression after neoadjuvant therapy reflected the resistance of tumor cell to clinical treatment, which enabled us to dynamically observe the changes of TME, so as to make the long-term effect of treatment and clinical prognosis more accurate prediction." (PMID 32733806, 2020). "IDO1 upregulation in tumor vessels may influence the infiltrating T-cell phenotypes and activation status." (PMID 32231867, 2020). "In line with a previous study, we did not observe any change in B16 tumor growth in wild-type and IDO1-deficient mice, suggesting that IDO1 is not a prerequisite for tumor growth." (PMID 32817121, 2020). "In addition, kynurenine generated by the IDO1 pathway, binding and activating the aryl hydrocarbon receptor (AhR), promotes Treg differentiation and immune suppression and fosters tumor cell survival and motility." (PMID 33986723, 2020). "Furthermore, anti-tumor T cells can be suppressed by Tregs and myeloid-derived suppressor cells (MDSCs) via IDO1, promoting tumor immune evasion." (PMID 32000802, 2020). "Now IDO1 is considered as an authentic immune regulator capable of fine-tuning both innate and adaptive immune responses under a variety of conditions, ranging from pregnancy and transplantation to infection, chronic inflammation, autoimmunity, and neoplasia." (PMID 33584695, 2020). "In some tumors, there is abundant lymphocyte infiltration around IDO1-expressing tumor cells, which means that IDO expression may be the result of IFN-γ expression and drug resistance mechanisms." (PMID 33117713, 2020). "The IDO1-specific inhibitor 1-methyltryptophan has been shown to significantly inhibit IDO1 activity, and the effects of 1-methyltryptophan in enhancing T-cell responses against tumor antigens, allograft antigens, and autoantigens in vivo have been validated." (PMID 32775303, 2020). "However, high glycolysis group was associated with lower infiltration of tumor-killing immune cells such as NKT cells and higher immune checkpoints expression such as PD-L1, CTLA4, FOXP3 and IDO1." (PMID 32070368, 2020). "The IDO1 is overexpressed by several tumor cell types and plays a key role in immunosuppression." (PMID 33194654, 2020). "Similarly, a synergistic nanoparticle containing a PS, protoporphyrin IX, and the IDO-1 inhibitor 1-methyltryptophan, conjugated via caspase-responsive peptides, also showed inhibition of the primary tumor and lung metastasis." (PMID 32317755, 2020). "The main clinical interest of IDO1 inhibitors has been in combination with anti-PD-1 agents, especially that preclinical in vivo studies demonstrated significant synergy and increased tumor shrinkage with this combination as compared to anti-PD-1 monotherapy." (PMID 32090113, 2020). "Indeed, high expression of IDO1 in tumour cells has been shown to correlate with worse clinical prognosis in patients with a variety of cancers, including colorectal, ovarian, endometrial, and hepatocellular carcinomas." (PMID 32466694, 2020). "IFN-γ is also a potent inducer of the enzyme IDO1, which may further suppress anti-tumor T cell functions." (PMID 32093058, 2020). "As we know, the check point of IDO1 could inhibit the function of cytotoxic T cells and cause immune escape in TME and tumor-draining lymph nodes." (PMID 32733806, 2020).
tumor (continued). "This suggests that IDO1+ tumor cells are either related to stem cells or to Paneth cells." (PMID 32444775, 2020). "However, the proportion of tumors with positive IDO1 staining was significantly higher in the group with higher levels of CD8+ TL tumor density than in the group with lower levels." (PMID 32194552, 2020). "IDO1 can be expressed by several cell types within the tumor microenvironment." (PMID 32231867, 2020). "In addition, we investigated the association between IDO1 and tumour mutation burden (TMB) and found that IDO1 was significantly correlated with TMB in BRCA and CESC." (PMID 32227579, 2020). "A recent study found that limitation of programmed cell death protein 1 (PD-1) inhibition might be due to an immunosuppressive tumor microenvironment based on IDO1 activation within macrophages." (PMID 32153576, 2020). "Tumor-reacting CD8+ T-cells and consequent IFNγ production cause expression of PD-L1 and other immunosuppressive proteins, such as indoleamine 2,3-dioxygenase (IDO1) and Foxp3, on tumor cells as a feedback mechanism, as shown in melanoma cells." (PMID 33260538, 2020). "Thus, EAPVs triggered PDT-mediated ICD as well as IDO-1 suppression, which supported tumor growth inhibition." (PMID 32317755, 2020). "A score of 0–4 was attributed to STAT1 and IDO1 levels in tumor and stroma compartments." (PMID 32444775, 2020). "It is likely that considering IDO1 as a moonlighting protein and targeting its signaling functions may provide much more benefit for successful immunotherapeutic maneuvers in neoplasia." (PMID 33584695, 2020). "Compared with NCRT, the tumor expression of IDO1 was more easily increased after NCT (p = 0.009)." (PMID 32733806, 2020). "Similarly, tryptophan 2,3-dioxygenase (TDO), which catalyzes the same reaction of IDO1, is expressed in a wide range of malignancies and has been shown to promote tumor progression and metastasis." (PMID 32536910, 2020). "Our results revealed the role of the IDO1 in tumour progression and immune responses that may lead to the development of IDO1 targeting therapy for assessing the efficacy and receptiveness in female cancer treatment." (PMID 32227579, 2020). "Given the important role of KP in immunosuppression and tumor growth, we screened BrCa models for the first rate-limiting enzyme of the KP, IDO1, which is known to play a significant role in modulating immune response using the publicly available, large population-based METABRIC BrCa dataset." (PMID 33109232, 2020). "mRNA correlated with protein abundance only for PD-1, PD-L1, and IDO1 and tumor mutation burden did not predict abundance of any protein targets." (PMID 32555523, 2020). "Interestingly, the combination of EGFRVIIICAR-T cells with the blockade of IDO1 significantly reduces tumor growth in a xenograft colon cancer model." (PMID 31379886, 2019). "In this case, higher expression of IDO1 may be a surrogate for a stronger spontaneous anti-tumor immune response to exert protective effects, resulting in a better prognosis." (PMID 31391111, 2019). "Such a nanoparticle was proposed as a platform for codelivery of anticancer drug (OXA) and potent inhibitor of IDO-1 (NLG919), an enzyme implicated in tumor immunosuppression through its ability to limit T-cell function and engage mechanisms of immune tolerance." (PMID 30871158, 2019). "Because both ARG1 and IDO1 act as immune checkpoint mechanisms in neoplasia, their functional “alliance” in specific immune cells could be remarkably effective in controlling adaptive immunity toward auto-antigens." (PMID 31354721, 2019). "Indeed, in vitro and in vivo studies have shown that IDO1 silencing can suppress tumor growth and restore T cell immunity in melanoma models." (PMID 30708988, 2019). "To know whether the IDO1 reduction caused by ABBV-075 has the universality, we further detected the effect of different BET inhibitors on the expression of IDO1 in different tumor cells." (PMID 31324754, 2019).
tumor (continued). "This process can be beneficial in adaptive antitumor immune response but can also be immunosuppressive by upregulation of molecules such as IDO1 in the tumor microenvironment or through feedback inhibition which may reduce antitumor activity." (PMID 31572681, 2019). "IDO1 differentially expressed in tumor cells and its expression could be induced with interferon gamma (IFN-γ)." (PMID 31324754, 2019). "However, CAI also stimulated IDO1-Kyn metabolic circuitry in the tumor microenvironment and facilitated tumor cell immune evasion." (PMID 31511064, 2019). "When tumor-bearing mice were treated with shRNA plasmids against IDO1 via a biolistic device—a low-pressure gene gun—tumor growth was significantly delayed in several tumor models, including murine subcutaneous bladder and colon tumor models, and orthotopic and metastatic liver tumor models." (PMID 30658461, 2019). "So it is difficult to directly detect the amount of IDO1 in the culture supernatant of tumor cells." (PMID 31391111, 2019). "In a recent preclinical study, in vivo tumor targeting of a newly developed IDO1 tracer, 1-(2-[18F]-fluoroethyl)-L-tryptophan ([18F]FETrp), was compared with [11C] AMT and increased SUVs were observed for [18F] FETrp compared with [11C] AMT in lung, breast, and brain xenografts." (PMID 31696402, 2019). "Moreover, increased Foxp3+ and reduced CD3+ tumor-infiltrating lymphocytes correlated with IDO1 expression." (PMID 31412566, 2019). "IDO1 is an enzyme that negatively regulates anti-tumor immunity." (PMID 31428574, 2019). "Furthermore, many human tumours have been shown to express IDO1, enhancing the suppression of effector T-cells and NK cells." (PMID 31358801, 2019). "Preclinical data demonstrated anti-tumor activity with IDO1 inhibition." (PMID 31921140, 2019). "These two IDO1 inhibitors showed low cell cytotoxicity, which indicated that they may exert their anti-tumor effect via immune modulation." (PMID 31195673, 2019). "IDO1 analysis was limited only to 25 tumours because of limited tumour sample availability." (PMID 31358801, 2019). "CD47 and IDO1 staining in tumours was ranked from low to high intensities." (PMID 31358801, 2019). "Moreover, a decrease in the numbers of regulatory T cells in the tumor was observed in mice that were treated with the IDO1-silenced DC." (PMID 31383907, 2019). "Based on the correlation between H2S and IDO1, and the role of IDO1 in tumor immunosuppression, it is possible to assume that H2S may have immunotherapeutic activity." (PMID 30777103, 2019). "Additionally, H2S donors effectively restricted the tumor development in H22 HCC-bearing mice via downregulating IDO1 expression, inducing T-effector cells and inhibiting MDSCs." (PMID 30777103, 2019). "However, the data reflects mixed level of IDO1 for cancer cells and stromal cells in tumor microenvironment." (PMID 31315643, 2019). "Then, IL-6 secreted by tumor or immune cells induces expressions of IDO1, such as IL-1β." (PMID 30708988, 2019). "We hypothesized that high density of tumour infiltrating Tregs, and IDO1+ TAMs, as well as high tumour CD47 and IDO1 expression would be associated with adverse outcome." (PMID 31358801, 2019). "Therefore, the inhibition of IDO1 activity is of special interest as a target for anti-cancer therapy in order to restore tumor immunity." (PMID 31417567, 2019). "Therefore, approaches combining IDO1 inhibitors and other complementary compounds or immune checkpoint inhibitors would probably produce synergistic benefits in terms of tumor growth and animal survival." (PMID 31511064, 2019). "Again, non-specific subtraction of the substrate for ARG1 may indirectly affect the host response to the tumor via effects on IDO1." (PMID 31354721, 2019). "Preclinical studies also demonstrated that radiotherapy could upregulate the expression of PD-L1 and IDO1 in tumor cells, which has been confirmed in human EC tissues." (PMID 30717285, 2019).
tumor (continued). "Along with tumor IDO1 expression, assessment of its activity may prevent overestimation of its role in the escape of cancer from immunosurveillance." (PMID 30150994, 2018). "An alternative strategy to limit negative regulation of T cell function and to break immunotolerance to tumor cells involves the modulation of L-tryptophan metabolism via the kynurenine pathway with the indoleamine 2,3-dioxygenase-1 (IDO1) inhibitor epacadostat." (PMID 29794999, 2018). "Protein expression of IDO1 was found to be high in a number of tumor samples; therefore, IDO1 may be a relevant therapeutic target to abrogate immune suppression." (PMID 29445380, 2018). "Herein, we assess the biochemical role of IDO1 in tumor metabolism and immune surveillance, and review current diagnostic and therapeutic approaches that are intended to increase the effectiveness of immunotherapies against highly aggressive and difficult-to-treat IDO-expressing cancers." (PMID 29445380, 2018). "In addition, IDO1 plays a key role in promoting tumor neovascularization by modulating the expression of interferon-γ (IFN-γ) and interleukin-6 (IL-6)." (PMID 30068361, 2018). "The role of IDO1 in tumor neoangiogenesis remains to be better elucidated as well." (PMID 30150994, 2018). "Moreover, immune infiltrate can be a “double-edged sword”, as products of effector immune responses, such as IFNγ, drive expression of immune checkpoint inhibitors in the tumor microenvironment, including PD-L1, IDO-1, etc.." (PMID 30376867, 2018). "To further evaluated the role of IDO1 in the growth of tumor cells and tissue-specific microenvironment, we grafted the TC-1 cells in IDO1−/− mice and measured the presence of macrophage, DCs and immunosuppressive cells in spleens and tumor tissues 21 post tumor cell transplantation." (PMID 30186285, 2018). "Thus, inhibiting the proliferation of tumor cells by suppressing the function of IDO1 has drawn much research attention." (PMID 30314496, 2018). "Thus, prior exposure of tumors to [neratinib + valproate] promotes anti-tumor immune responses through multiple overlapping mechanisms including infiltrating NK cells, M1 macrophages and reduced IDO-1 and ODC expression." (PMID 29464055, 2018). "IDO1 has been shown to induce the expression of a L-Trp transporter in human tumor cells." (PMID 29615752, 2018). "Other potential strategies, such as combining IDO1 inhibitors with IDO1 vaccines may also produce synergistic anti-tumor effects." (PMID 30068361, 2018). "However, tumor- IDO1/HLA-DR expression was most predictive of survival (OS, p=0.0005, HR = 0.4; PFS, p=0.0015, HR = 0.42), outperforming PD-L1 and INF-G signature." (PMID 30400835, 2018). "This variable suggests a differential immunosuppressive role of IDO1 across tumor types." (PMID 29805749, 2018). "The inhibition of IDO1 activity could restore the function of T cells and NK cells and overcome the tumor immune tolerance." (PMID 30519541, 2018). "We will then highlight the role of IDO1-related signaling pathways in the tumor microenvironment." (PMID 30068361, 2018). "IDO1 levels were determined in the tumor and stroma, and stratified using median cut-point." (PMID 29037255, 2017). "As a final example, IDO-1 inhibition is a powerful approach for promoting tumor immunity." (PMID 28421069, 2017). "The identification of distinct roles for the two pITIMs of IDO1 may pave the way to innovative strategies in treating autoimmune, chronic inflammatory and neoplastic diseases by either enhancing or terminating IDO1's activity, as appropriate." (PMID 27696702, 2017). "Formerly thought as an effector enzyme of the immune system debarring pathogen bacteria from the essential amino acid l-Trp, IDO1 has experienced a new lease of life with seminal discoveries about its involvements in mediating maternal immune tolerance and the tumor immuno-editing process." (PMID 30108849, 2017). "IDO1 is currently well recognized as a potent target of anti-tumor therapies." (PMID 29285252, 2017).